USP46 (ubiquitin specific peptidase 46)
Diseases named in the same sentence as USP46 in open-access papers (continued):
Sharing a sentence is not in itself a finding about the gene and the disease.
prostate carcinoma (1 paper, 2018). A carcinoma that arises from epithelial cells of the prostate gland. "To validate the shared role of USP12 and USP46 in prostate cancer cell biology we individually silenced both genes in PC cells and performed full transcriptome analysis to establish the extent of their shared functions." (PMID 29861848, 2018).
renal cell carcinoma (1 paper, 2020). "Previous studies have shown that ubiquitin-specific protease 46 (USP46) is a tumor suppressor in colon cancer and renal cell carcinoma." (PMID 33029497, 2020).
cancer (13 papers, 2018 to 2026). A tumor composed of atypical neoplastic, often pleomorphic cells that invade other tissues. "Furthermore, it remains to be investigated if there are recurrent mutations in USP46 genes in patients with cancer and if, subsequently, they correlate with other known driver mutations." (PMID 33029497, 2020). "PHLPP1, histone H2A, and H2B have been identified as substrates of both USP12 and USP46, suggesting that USP12 and USP46 are associated with AKT signaling in cancer cells and transcription activation in Xenopus embryo." (PMID 39482856, 2025). "Using the cBioPortal to assess 9,125 tumor samples across 33 cancer types in The Cancer Genome Atlas39,40, we found a significant correlation between USP46 gene alterations and decreased overall cancer patient survival." (PMID 37798301, 2023). "USP46 belongs to ubiquitin specific proteases of DUB family and is involved in replication and pathologies of cancer-causing viruses." (PMID 35008200, 2021). "The answers support the presence of the proposed E6-USP46-Cdt2-Set8-H4K20me1 signal transduction process in carcinogenesis by HPV and set the stage for screening for inhibitors of USP46 that will be useful for therapy of such cancers." (PMID 35008200, 2021). "The most frequent cMDT disrupting interactions in over 90% of samples of a cancer type were those from the genes USP46, WDR74, RPS19, BOLA2B, NDUFA9, and LAMA3." (PMID 32879328, 2020). "Recent studies have identified other substrates of USP46 that have important functions in cancer progression." (PMID 33029497, 2020). "This manuscript provides a proof of principle for USP12 and USP46 targeted inhibition in cancer therapy." (PMID 29861848, 2018). "Accordingly, the identification of USP46 small molecule inhibitors may provide a novel therapeutic option to combat cancers dependent on Wnt ligand stimulation." (PMID 37798281, 2023). "Given the role of Wnt signaling as a major driver of tissue growth, we asked whether USP46 is altered in human cancers." (PMID 37798301, 2023). "Earlier we had identified a protein target, USP46 that can be inhibited to block the cancer growth." (PMID 35008200, 2021). "Thus, the cancer-specific expression of the transcript ENST00000451218 is disabling the tumor suppressor function of USP46." (PMID 32879328, 2020). "We found that cancer tissues had significantly lower levels of USP46 messenger RNA (mRNA)." (PMID 33029497, 2020). "Thus, inhibitors that target USP46 may have broad applicability for treating Wnt-driven human cancers." (PMID 37798301, 2023). "Beyond AKT, USP12 also stimulates STAT1 signaling and USP46 regulates the cell cycle through stabilizing the CRL4Cdt2 E3 ubiquitin ligase complex, which promotes proliferation of HPV-transformed cancers." (PMID 41533576, 2026). "Oncogenic E6 recruits a cellular deubiquitinase to stabilize critical cellular proteins, and because the E6-USP46-Cdt2-Set8 pathway is important in HPV-induced malignancies, USP46 is a target for cancer therapy." (PMID 35804810, 2022). "Future work will shed more light into the functional ties between USP46 and AKT during cancer therapies." (PMID 33029497, 2020). "Another study also showed that USP46 is required for the proliferation of HPV-transformed cancers and derived cancer cells, indicating that USP46 can be essential for the survival of HPV-transformed cancers." (PMID 32085533, 2020).
tumor (13 papers, 2013 to 2025). "UAF1/USP1, UAF1/USP12, and UAF1/USP46 complexes play vital roles in DNA repair processes and tumor pathogenesis." (PMID 33247121, 2020). "Thus, depletion of USP46 inhibits HPV-transformation-induced tumor growth through the E6-USP46-Cdt2-Set8 pathway." (PMID 35283827, 2022). "USP46 can promote MST1 kinase activity through deubiquitination to inhibit tumor growth and metastasis, suggesting that USP46 may be a potential therapeutic strategy for HCC." (PMID 35875077, 2022). "Our data indicates that inhibition of USP12 and USP46 activity with galeterone, or other compounds may be a very effective anti-tumour strategy, however galeterone effects in those PC patients expressing AR V may be limited." (PMID 29861848, 2018). "USP19, USP44, USP46, and USP53 has been revealed as potential tumor suppressor in KIRC in the previous study." (PMID 37259026, 2023). "Moreover, USP46 protein could mediate the stability of CDT2 and promote the growth of HPV-positive tumors, suggesting the potential role of DTL in tumor progression." (PMID 40385396, 2025).
neurological disorders (3 papers, 2017 to 2023). "Ubiquitin-specific protease 46 (USP46), a member of the cysteine protease family with deubiquitinating function, has previously been reported to be associated with neurological disorders." (PMID 37576883, 2023). "Ubiquitin-specific protease 46 (USP46) is a member of the cysteine protease family which functions as a deubiquitinase and has been associated with neurological disorders and behavioral abnormalities." (PMID 33029497, 2020). "It will be interesting to learn if mutations in USP46 or its regulators are associated with other neurological disorders given the importance of USP46 in both glutamatergic and GABAergic signaling." (PMID 29302259, 2017).
infection (2 papers, 2022 to 2025). The state of being infected such as from the introduction of a foreign agent such as serum, vaccine, antigenic substance or organism. "Furthermore, there were nine proteins that were specifically detected at 7 days post-infection (Saa2, Trappc1, Cxadr, Armc8, Hbxip; Lamtor5, Prppsap2, Usp46, Pcdh10, Neo1)." (PMID 36061859, 2022). "Transcriptomic profiling revealed infection-induced upregulation of DUBs, particularly USP25, USP46, and OTUD7B." (PMID 40899844, 2025).
USP46 also shares sentences with these, for which no sentence is quoted: Anxiety (2 papers); schizophrenia (2); embryonal carcinoma (1); essential tremor (1); Huntington disease (1); liver cancer (1); lung squamous cell carcinomas (1); multiple myeloma (1); myocardial ischemia (1); ovarian carcinoma (1).